ZC3H13 (zinc finger CCCH-type containing 13)
Diseases named in the same sentence as ZC3H13 in open-access papers (continued):
Sharing a sentence is not in itself a finding about the gene and the disease.
tumor (continued). "The expression of ZC3H13 of these cells might inhibit T and NK cells from infiltrating into the tumor microenvironment as ZC3H13 was negatively correlated with the infiltration of TIICs in KIRC." (PMID 34497769, 2021). "We found that the copy number loss of ZC3H13, FTO, YTHDC2, WTAP and ALKBH5 decreased the protein expression in tumor samples, and meanwhile, patients with amplification of IGF2BP3, HNRNPA2B1 and IGF2BP2 presented higher expression level of these three proteins than normal tissues." (PMID 32710725, 2020). "Increasing evidence has shown that ZC3H13 plays an important role in inhibiting tumor progression." (PMID 32742465, 2020). "Since hyperactivation of the NFκB promotes tumor proliferation and invasion, ZC3H13 might function as an oncogene." (PMID 33072775, 2020). "Zinc finger CCCH-type containing 13 (ZC3H13) is a highly expressed oncogenic m6A writer that modulates centromere protein K (CENPK) and cytoskeleton-associated protein 2 (CKAP2) expression to promote malignant properties, tumour stemness and chemoresistance in CC patients (Refs 45, 46)." (PMID 39377535, 2024). "Additionally, ZC3H13 was significantly related to TIICs in most tumor microenvironments." (PMID 34497769, 2021). "However, some studies have shown that ZC3H13 could act as an oncogene to activate the NF-kB signaling pathway to promote tumor proliferation and invasion." (PMID 34497769, 2021). "Emerging evidence indicates that Zinc Finger CCCH-Type Containing 13 (ZC3H13), a core component of the M6A methyltransferase complex, exhibits tumor-suppressive functions in cancer progression." (PMID 41312360, 2025). "Most regulators, such as METTL3, YTHDF1, IGF2BP3, and RBMX, were upregulated in tumor tissues, while METTL14 and ZC3H13 were downregulated." (PMID 40916616, 2025). "UMAP-based expression overlays revealed that NSUN2, YTHDC1, ALKBH5, ZC3H13, and TRDMT1 were predominantly expressed within epithelial clusters, consistent with a tumor-intrinsic regulatory role." (PMID 40565233, 2025). "Except for ZC3H13, the other three genes (CBLL1, ELAVL1 and YTHDF1) were positively correlated with purity state of tumor cell in LUSC." (PMID 36261786, 2022). "ZC3H13 was mainly expressed in smooth muscle cells, fibroblasts, and TXNDC12 was mainly expressed in tumor/epithelial cells, macrophages, and endothelial cells." (PMID 36712973, 2022). "Compared with normal counterparts, 4 DEMGs (FTO, ZC3H13, METTL14 and RBM15B) were significantly down-regulated in tumor samples, while the remaining 11 genes were upregulated in tumor samples." (PMID 36536402, 2022). "Taken together, TIMER analysis indicated that METTL14, ZC3H13, and YTHDC1, as key regulators of m6A modifications, were closely related to tumor immune infiltration in EC." (PMID 34230220, 2021). "By comparing 50 normal and 374 tumor tissues, METTL14, YTHDC1, ZC3H13, ALKBH5, YTHDF2, and RBM15 had extremely lower expression in tumor tissues (p < 0.001)." (PMID 34277622, 2021). "It appeared that IGF2BP1/3, ELAVL1, HNRNPA2B1, HNRNPC, KIAA1429, RBM15, LRPPRC, FMR1, YTHDF1/2 are highly expressed in the tumor while FTO, METTL14/16, WTAP, YTHDC1 and ZC3H13 are down-regulated." (PMID 35095993, 2021). "Specifically, YTHDF1, IGF2BP2, KIAA1429, RBM15, IGF2BP1, ZC3H13, and METTL3 were significantly up-regulated in tumor tissues by unpaired T-tests (P < 0.05), while ALKBH5, YTHDC2, and METTL14 were significantly down-regulated (P < 0.01)." (PMID 34149792, 2021). "Five m6A-related genes (ZC3H13, METTL14, YTHDF2, YTHDF3 and HNRNPA2B1) showed significantly downregulated in tumor tissue, while seven regulators (YTHDC2, FTO, WTAP, METTL3, ALKBH5, RBM15 and KIAA1429) was remarkably upregulated in ccRCC." (PMID 32419773, 2020). "Interestingly, another study has reported that ZC3H13 can promote m6A-mediated expression of the tumor suppressor A1BG-AS1, highlighting the anti-tumor role of ZC3H13 in PCa." (PMID 38610981, 2024).
tumor (continued). "ZC3H13 and METTL14 were strongly related to APC (an antagonist of the Wnt signaling pathway), meaning that ZC3H13 and METTL14 are involved in the regulation of invasion, proliferation, and metastasis of tumor cells." (PMID 36261786, 2022). "The results showed that expression levels of METTL3, VIRMA and CBLL1 were significantly increased, while expression levels of METTL14 and ZC3H13 were significantly decreased in HCC, which was closely related to clinicopathological factors, such as tumor stage and prognosis." (PMID 35223847, 2022). "ZC3H13 expression was demonstrated to be positively correlated with the infiltration level of immune cells (i.e., CD8 T cells), which indicated an immune-activated condition, facilitating recognition and elimination of tumor cells and then improving prognosis." (PMID 34422799, 2021). "Four genes (MRPL54, ZC3H13, IFIT5, and PPARGC1A) were downregulated and may function as tumor suppressor genes in HCC, and showed a positive correlation with prognosis." (PMID 33251144, 2020). "On the contrary, METTL14, ZC3H13, FTO, and WTAP are low-expressed in tumor tissues." (PMID 32258108, 2020). "Similarly, the three writers, METTL3, METTL16, and ZC3H13 have all been shown to influence PTC progression, tumor size, and prognosis, and as the up- or down-regulation of the enzymes is associated with PTC, they may also be useful as biomarkers of disease." (PMID 40243425, 2025). "Notably, expression of the tumor suppressors METTL14 and ZC3H13 was positively correlated with the infiltration of Tcm cells, Th17 cells, and eosinophils, consistent with previous findings that these cells are associated with a favorable prognosis of malignant tumors." (PMID 35223847, 2022). "Co-expression analysis revealed that METTL14 and ZC3H13 had a strong positive correlation with APC, an antagonist of the Wnt signaling pathway, indicating they might cooperate in regulating proliferation, invasion, and metastasis of tumor cells." (PMID 33363011, 2020). "Interestingly, our prognostic model demonstrated that the expression level of ZC3H13 was positively correlated with the prognosis of HCC, suggesting that it might function as a tumor suppressor in HCC." (PMID 32733931, 2020). "Currently, there are no studies elaborating the role of ZC3H13 in KIRC, especially its relationship with tumor immune characteristics." (PMID 34497769, 2021). "Similarly, ZC3H13 and TRDMT1, despite inclusion in multiple prognostic signatures (e.g., BLCA and CESC), showed moderate-to-low expression in fibroblasts and immune cells, supporting roles in stromal remodeling rather than direct tumor cell regulation." (PMID 40565233, 2025).
cancer (53 papers, 2019 to 2025). A tumor composed of atypical neoplastic, often pleomorphic cells that invade other tissues. "When the genomic alterations are investigated, most of the m6A regulators harbor SNVs across different cancers, with ZC3H13, VIRMA, and PRRC2A having higher mutation frequencies." (PMID 39457524, 2024). "Most of the m6A regulators are found to be mutated across the cancers, with ZC3H13, VIRMA, and PRRC2A having a higher frequency rate." (PMID 39457524, 2024). "ZC3H13 was upregulated in patients with high cancer risk, whereas METTL3, KIAA1429, YTHDF1, and YTHDF2 were downregulated." (PMID 32631107, 2020). "Using the Gene Set Enrichment Analysis (GSEA), we found that IGF2BP1, VIRMA, and ZC3H13 are all associated with pathways in cancer and WNT signaling pathway." (PMID 32950970, 2020). "The unique microenvironment of cancer cells likely enables ZC3H13 to activate the EMT process and disrupt epithelial integrity." (PMID 40774945, 2025). "We obtained expression data for ZC3H13 in pan-cancer from the public database GEPIA and found that ZC3H13 expression is significantly elevated in STAD." (PMID 40774945, 2025). "The expression of zinc finger CCCH-type containing 13 (ZC3H13) plays a crucial role in the development of malignant tumor." (PMID 41256854, 2025). "Initially, we examined the expression of ZC3H13 in the Genotype-Tissue Expression (GTEx) and The Cancer Genome Atlas (TCGA) dataset." (PMID 40959082, 2025). "To gain insight into the mechanism by which ZC3H13 promotes the malignant progression of cancer, we further analyzed the results from MeRIP-seq, RNA-seq, and multi-omics analyses." (PMID 40774945, 2025). "From a translational perspective, the cancer-promoting role of ZC3H13 highlights its potential as a therapeutic target for GC, thereby reducing collateral damage to healthy tissues." (PMID 40774945, 2025). "The expression and function of ZC3H13 are altered in several cancers, including breast cancer, cervical cancer, and hepatocellular carcinoma, among others." (PMID 40243425, 2025). "Zinc finger CCCH-type containing 13 (ZC3H13) is an important cancer-related RNA-binding protein, and has been found to be an m6A regulator that acts as a methylation transferase." (PMID 38351022, 2024). "Next, to make our analysis more reliable, the expression of ZC3H13 in different cancers was further validated by the GEPIA database." (PMID 35278064, 2022). "It is noteworthy that the KEGG results of transcriptional misregulation in cancer and the JAK-STAT signaling pathway are common across multiple databases as the function of the genes associated with ZC3H13." (PMID 35582419, 2022). "High ZC3H13 expression was associated with low expression of the RIBOSOME, positive correlation of the MAPK signaling pathway, pathways in cancer and mTOR signaling pathway, NOTCH signaling pathway." (PMID 36712973, 2022). "The functional analysis results showed that the following biological processes were enriched in the genes co-expressed with ZC3H13: transcriptional misregulation in cancer." (PMID 35582419, 2022). "Among the signaling pathways showing the greatest correlation with genes co-expressed with ZC3H13 was the KEGG pathway hsa05202 (transcriptional misregulation in cancer)." (PMID 35582419, 2022). "The results suggested that the SNVs of the 20 m6A regulators altered in 74.8% TCGA samples across cancer types, and the waterfall plots presented the top ten SNVs-changed genes, such ZC3H13, YTHDC2, and IGF2BP1." (PMID 35003212, 2021). "The differential expression patterns of ZC3H13 in pan-cancers prompted us to explore its prognostic value." (PMID 34497769, 2021). "Collectively, the roles of DNAJC6, IGF2BP3, and ZC3H13 in regulating cancer progression as mentioned in above studies are consistent with our present study, indicating the results based on our study are reliable." (PMID 34312475, 2021).
cancer (continued). "We comprehensively analyzed the expression, prognostic significance and immunological role of ZC3H13 in pan-cancers and systematically correlated ZC3H13 with TME cell-infiltration, ICB response and targeted therapy in KIRC." (PMID 34497769, 2021). "In this study, we first explored the expression pattern and prognostic value of ZC3H13 in pan-cancers and its relationship with immune characteristics through pan-cancer analysis." (PMID 34497769, 2021). "It was discovered that the expression level of ZC3H13 was significantly downregulated in both cancer tissue and HCC cell lines." (PMID 34422799, 2021). "The results suggest that the mRNA and protein levels of ZC3H13 are both high in cancer tissues compared with the normal control." (PMID 32950970, 2020). "According to published studies, ZC3H13 exhibited heterogeneous roles in various types of human cancer." (PMID 33072775, 2020). "A fusion between MLL1 and ZC3H13 was found in cancer cells; this fusion also showed the loss of the SET domain as we observed in our TCGA analyses." (PMID 30548174, 2019). "Recent reports have highlighted the controversial role of ZC3H13 in cancer progression." (PMID 40774945, 2025). "ZC3H13, VIRMA, and PRRC2A almost have a higher mutation frequency rate in all cancer types." (PMID 39457524, 2024). "ZC3H13 was a tumor suppressor gene in a variety of types of cancer." (PMID 37301543, 2023). "Functional and pathway enrichment analyses indicated that ZC3H13 might be involved in transcriptional dysregulation or the JAK-STAT signaling pathway in cancer." (PMID 35582419, 2022). "In this study, we performed pan cancer analysis for ZC3H13 expression and prognosis using The Cancer Genome Atlas (TCGA) and Genotype-Tissue Expression (GTEx) data and found that ZC3H13 might be a potential tumor suppressor gene in HCC." (PMID 35278064, 2022). "Besides that, HNRNPA2B1, YTHDC1, METTL14, WTAP, and ZC3H13 were downregulated in cancer tissues, whereas VIRMA had opposite alterations between these two databases." (PMID 33225598, 2021). "Additionally, the infiltration of cancer-promoting TIICs, including regulatory T cell, plasmacytoid dendritic cells, neutrophils, and type 2 T helper cells, was significantly increased in the high ZC3H13 group." (PMID 34497769, 2021). "m6A regulators include writers (METTL3, METTL14, KIAA1429, and ZC3H13), erasers (ALKBH5 and FTO) and readers (YTHDF1/2/3, IGF2BP1/2/3), which are thought to play important roles in regulating cancer progression." (PMID 40774945, 2025). "We downloaded survival data for GC patients from the Asian Cancer Research Group (ACRG) and The Cancer Genome Atlas (TCGA) databases and found that patients with the overexpression of ZC3H13 had decreased overall survival (OS) and relapse-free survival (RFS)." (PMID 40774945, 2025). "Among the 68 HCC patient specimens that underwent immunohistochemical staining, all cancer tissues were positive for METTL14, YTHDF2, and ZC3H13 staining in contrast to the adjacent tissues." (PMID 36936652, 2023). "Among them, there were 12 m6A regulatory genes, including IGF2BP1, with a significantly higher expression in LUAD tissues compared with para-carcinoma tissues, while FTO, METTL14, WTAP, and ZC3H13 showed a significantly lower expression." (PMID 36249006, 2022). "Whereas, ZC3H13 and FTO were highly expressed in normal tissues and low expressed in cancer tissues." (PMID 34521394, 2021). "For the three selected regulators, IGF2BP1, VIRMA, and ZC3H13, the GSEA study result indicated that they were also all correlated with pathways in cancer and WNT signaling pathways." (PMID 32950970, 2020). "In contrast, ZC3H13, IGF2BP1, WTAP, FTO, and YTHDC2 were downregulated in ≥four cancer types." (PMID 35211628, 2022).
cancer (continued). "Compared with the control group, expression levels of HNRNPC, YTHDF1, KIAA1429, RBM15, YTHDF2, and METTL3 in cancer group were significantly up-regulated (P < 0.05), while expression levels of FTO, ZC3H13, METTL14, YTHDC1, and WTAP in cancer group were significantly down-regulated (P < 0.05)." (PMID 33193582, 2020). "In conclusion, akin to METTL3, METTL4, METTL16, WTAP, RBM15/15B, VIRMA, and ZC3H13, the potential influence of YTHDC1, YTHDC2, YTHDF, IGF2BPs, the HNRNP family, eIF3, FTO, and ALKBH3/5 on autophagy is intertwined with their roles in RNA metabolism, collectively regulating autophagy in cancer." (PMID 38148841, 2023). "Although the regulatory subunits of the m6A writers WTAP, VIRMA, ZC3H13, and HAKAI have been reported to be associated with cancers, whether their functional roles in cancers are dependent on m6A modification is not reported." (PMID 32245947, 2020). "Thus, we speculated ZC3H13, IGF2BP3, and DDX19B might participate in the occurrence and development of HCC through regulating their correlated AS events and inducing dysregulation of above cancer-related pathways." (PMID 34312475, 2021).
ZC3H13 also shares sentences with these, for which no sentence is quoted: sarcoma (3 papers); cholangiocarcinoma (2); kidney cancer (2); adenocarcinoma (1); anal squamous cell carcinoma (1); autoimmune disease (1); bladder urothelial carcinoma (1); endocervical adenocarcinoma (1); endometriosis (1); infertile (1); inflammatory bowel disease (1); lymphoma (1); meningioma (1); myocardial infarction (1); neuroblastoma (1); oral carcinoma (1); osteosarcoma (1); ovarian serous cystadenocarcinoma (1); periodontitis (1); triple-negative breast carcinoma (1); viral infections (1).